ENSG00000201465
Synonyms: LOC124900243
Gene: Small nucleolar RNA gene on chromosome 7 (138,187,998 to 138,188,129, reverse strand). Ensembl gene ENSG00000201465.
Gene Ontology:
Biological process: RNA processing
Cellular component: nucleolus
Homologues: Orthologues: rat LOC120096114 (77% identical), rat LOC120095739 (76% identical), rat LOC120102643 (71% identical), rat LOC120095430 (64% identical), rat LOC120097226 (48% identical). Paralogues in human: SNORA51 (80% identical).